RNU6-1280P (RNA, U6 small nuclear 1280, pseudogene)
Gene: Small nuclear RNA gene on chromosome 15 (85,651,522 to 85,651,628, reverse strand). Ensembl gene ENSG00000202081.
Homologues: Orthologues: chimpanzee U6 (99% identical), macaque U6 (87% identical). Paralogues in human: RNU6-1060P (82% identical), RNU6-125P (82% identical), RNU6-15P (82% identical), RNU6-672P (82% identical), RNU6-949P (82% identical), RNU6-1011P (81% identical), RNU6-12P (81% identical), RNU6-132P (81% identical), RNU6-13P (81% identical), RNU6-31P (81% identical), RNU6-32P (81% identical), RNU6-33P (81% identical), and 1285 more.